ATM (ATM serine/threonine kinase)
Diseases named in the same sentence as ATM in open-access papers (continued):
Sharing a sentence is not in itself a finding about the gene and the disease.
tumor (continued). "An ATM inhibitor, M3541, inhibited the IR-induced initiation of the ATM-dependent DNA repair pathway, inactivated the G1/S cell cycle checkpoint, and induced tumor cell death by disturbing mitosis." (PMID 37109350, 2023). "Therefore, inhibition of ATM proteins is an alternative approach to suppressing tumor growth; in addition, compared to other DDR-targeted agents such as PARP inhibitors, the study of ATM inhibitors is still in the early stages." (PMID 36902170, 2023). "The data above represent the progression of ATM inhibitors in tumor treatment." (PMID 37109350, 2023). "Interestingly, for three patients enrolled based on ATM alterations (two identified by ctDNA analysis, one by tumor NGS), we determined that their enrollment alterations were derived from CHIP rather than their tumor." (PMID 37277454, 2023). "Importantly, Gal-9 blockade combined with genetic depletion or pharmaceutical inhibition of ATM synergistically induces potent anti-tumor immunity and markedly reduces tumor growth in syngeneic mouse models." (PMID 36778120, 2023). "Among the 30 patients with tumors evaluated for ATM immunohistochemical (IHC) analysis, two-thirds of samples (20/30) displayed loss of protein expression, whereas 33% (10/30) had varying levels of tumor cell ATM protein expression (median H-score 95; IQR 46–190)." (PMID 37277454, 2023). "Currently, the penetrance for each tumor is still not fully ascertained, but odds ratios for specific malignancies in ATM variant carriers are emerging." (PMID 37509701, 2023). "Case 13, a 78 year-old man with GBM, +7/−10 and ATM mutation were found in the CSF ctDNA but not in the tumor DNA, at the same time, loss of CDKN2B was only found in tumor DNA." (PMID 37822669, 2023). "We then inoculated syngeneic BALB/c mice with control or ATM KD CT26 tumor cells, and found that ATM-depleted cells formed smaller tumors compared with vector control (VC), indicating a tumor-suppressive effect of ATM depletion." (PMID 36778120, 2023). "Additionally, some DGC patients tested negative for CDH1/CTNNA1 gene but had pathogenic variants in related tumor susceptibility genes, such as BRCA2, ATM, SDHB, PRSS1, MSR1, STK11, and PALB2." (PMID 37393258, 2023). "After analysis of the tumour sequencing data, there was only one participant that had no possibly detectable ctDNA variant because of the panel design (a pathogenic ATM variant not included in the GI cfDNA panel)." (PMID 36831507, 2023). "The specific role of different molecular components warrants further investigation in relevant cellular and animal models, but these results suggest that ATM inhibition could enhance the immunomodulatory effect of radiation in the tumor environment." (PMID 36656721, 2023). "One tumor, with a negative GI status by Myriad MyChoice, had four ATM loss-of-function variants and a pathogenic BRCA2 variant." (PMID 38067228, 2023). "A series of DDR-related genes, such as ATM and DNA-PKcs, can facilitate tumor cell immune evasion." (PMID 37457685, 2023). "For example, a clinical trial of paclitaxel with or without olaparib in second-line treatment of advanced metastatic gastric cancer examined reduced ATM expression, defined as less than 25% tumor cells staining positive in an immunohistochemistry assay, as a marker of benefit." (PMID 36975505, 2023).
tumor (continued). "Importantly it was also demonstrated that ATM inhibition enhanced the effectiveness of Bragg peak protons in the suppression of tumour growth in a patient-derived xenograft model." (PMID 36902352, 2023). "Similarly, ATM inhibition in a mouse model resulted in inhibition of senescence induction and increased tumor size and invasiveness." (PMID 37886943, 2023). "Reduced expression of PD-L1 was found after applying WEE1 and ATM inhibitors to tumor cells, which may result from reduced expression levels of CMTM6 and GSK-3β." (PMID 37305685, 2023). "ATM analogs antagonize TPMs in tumor tissues with significant targeting properties." (PMID 37686101, 2023). "ATM inhibitors induce cell death and are involved in tumor immune responses in different ways." (PMID 37109350, 2023). "NSCLC patients with KRAS and STK11 co-mutations are also more likely to carry the mutations in KEAP1 and ATM genes and are predisposed to the development of a cold tumor (without immune cells in tumor microenvironment)." (PMID 37509393, 2023). "The expression of ATM in tumor tissue is lower than in normal tissue (P=0.0062)." (PMID 37745716, 2023). "Looking at the type of ATM mutation with VAF and confirming tATM expression at the baseline by IHC along with an understanding of the molecular phenotype of tumours could aid in mapping treatment responses to ATM status for certain patient populations." (PMID 37627223, 2023). "AZD6738 also showed single-agent anti-tumor efficacy in ATM-deficient but not ATM-proficient xenograft mice." (PMID 37511442, 2023). "However, when ATM is present in tumor cells, it confers resistance to ionizing radiation and DNA-damaging agents." (PMID 36672401, 2023). "A feature displayed by the Mre11ATLD/ATLD mutation might explain the different tumor-promoting activities of MRN component Mre11 versus Nbs1 and ATM." (PMID 37754262, 2023). "Although early clinical studies investigating ATR inhibition in tumors harboring ATM mutations or lacking ATM protein expression have shown preliminary signals of anti-tumor activity, the optimal method for identifying ATM LOF in a broader population remains to be established." (PMID 37277454, 2023). "Based on our and other findings that ATM inhibition sensitize tumors to both anti-PD-1 21,22 and anti-Gal9 therapies, it is conceivable that triple combination of ATMi with anti-PD-1 and anti-Gal-9 would produce an even more potent anti-tumor effect." (PMID 36778120, 2023). "Both types of signaling are likely to play a part in ATM's ability to limit tumor growth." (PMID 37081847, 2023). "Inhibiting the ATM/Chk2 DNA damage checkpoint pathway triggers replication stress and the accumulation of cytosolic DNA, activating the innate immune response mediated by the DNA sensor STING in ARID1A‐deficient tumours." (PMID 38041544, 2023). "Another phase I dose-escalation study (NCT03225105) assessed the safety and anti-tumor activity of the ATM inhibitor M3541 (50–300 mg) in combination with fractionated palliative radiotherapy (30 Gy in 10 fractions) in 15 patients with solid tumors (including two CRC patients)." (PMID 36230796, 2022). "Next, we tested whether ATM targeting affects tumor growth in vivo using different murine tumor models." (PMID 36353752, 2022). "For example, ATM regulates radiation-induced autophagy through the mTOR pathway, MAPK14 pathway, JNK pathway, and PI3KIII pathway, and complete lack of ATM function results in the failure of autophagy induction in tumor cells or switches the cell stress response to senescence." (PMID 35888608, 2022). "Tumor cells are more susceptible to RT than normal cells due to their high replication rate and defects in DNA damage response (DDR) pathways (such as mutations in ATR or ATM)." (PMID 36457125, 2022). "ATM has significant prevalence between 2 and 5% across tumour types, with 5.4% in prostate." (PMID 34979999, 2022).
tumor (continued). "Similarly to the role of ATM in cellular senescence, CHEK2 is a multiorgan tumor susceptibility gene involved in the induction of replication- and oncogene-triggered senescence to block hyperproliferation and subsequent tumorigenesis." (PMID 35406559, 2022). "ATM inhibition makes some tumors more sensitive to radiation therapy, but this may depend on the genetic makeup of the tumor." (PMID 36139666, 2022). "For the large majority of the VUSs analyzed in this study, we did not observe loss of the ATM protein in tumor tissue." (PMID 36555667, 2022). "Stromal ATM targeting attenuated myoCAF accumulation and suppressed tumor growth." (PMID 36353752, 2022). "And, furthermore, the activation of ATM was prolonged when compared to other tumor types." (PMID 36408163, 2022). "ATM inhibition prevents the expression of stress molecules on tumor cells." (PMID 36071479, 2022). "Similar to traditional appendix-derived PMP, our patient’s tumor harbored non-targetable mutant KRAS-GNAS co-mutations with ATM mutant positivity." (PMID 35272690, 2022). "Pharmacological inhibitors of DNA damage response (DDR) proteins, such as the ataxia-telangiectasia mutated (ATM) and ataxia-telangiectasia and Rad3-related (ATR) kinases and poly (ADP-ribose) polymerase (PARP), have been developed to overcome tumor radioresistance." (PMID 35954456, 2022). "For example, ATM (ataxia telangiectasia mutated) inhibition promotes mtDNA leakage into the cytoplasm to activate cGAS-STING signaling and enhance lymphocyte infiltration into the tumor microenvironment." (PMID 35002511, 2022). "Furthermore, ATM‐associated DNA damage response cooperates with MAPK and mTOR signaling pathways to control citrate‐induced tumor cell growth arrest and senescence." (PMID 34747157, 2022). "Furthermore, ATM‐associated DNA damage response (DDR) cooperated with MAPK and mTOR signaling pathways to control citrate‐induced tumor cell growth arrest and senescence." (PMID 34747157, 2022). "IFN-γ derived from immunotherapy-activated CD8+T cells and radiotherapy-activated ataxia telangiectasia mutated (ATM) can independently or synergistically suppress the expression of SLC7A11 to reduce cystine uptake, enhance tumor lipid oxidation and ferroptosis, and improve tumor control." (PMID 36003368, 2022). "It is still unclear whether pharmacological inhibition of DNA-PKcs kinase activity may dampen anti-tumour immunity in contrast to inhibition of other DDR kinases described such as ATM or ATR." (PMID 36106115, 2022). "Taken together, these results show the potential challenges in using radiotracers to assess ATM status but highlight the potential benefit of developing similar radiofluorinated ATM inhibitors for the non-invasive assessment of drug pharmacokinetics and tumour distribution." (PMID 35962885, 2022). "However, ATM inhibitor monotherapy is generally therapeutically ineffective in conventional preclinical tumor models, where the stromal component is typically absent." (PMID 36353752, 2022). "We provide a comprehensive set of genes whose inactivation sensitizes cells to multiple ATMi, which may thus represent biomarkers of the tumor cells’ response to ATM inhibition." (PMID 35717336, 2022). "In the PROfound study, BRCA and ATM mutations identified in ctDNA showed 81% positive percentage agreement and 92% negative percentage agreement with matched tumor tissues." (PMID 35924163, 2022). "As the number of unrepaired DSBs is a major determinant of cellular radiosensitivity, the reduced impact of ATM inhibition on DSB repair foci in the HPV+ tumor cells should result in less effective radiosensitization in clonogenic assays compared to the HPV− strains." (PMID 35719921, 2022).
tumor (continued). "In models of EGFR mutant non-small cell lung cancer (NSCLC), tumor cells that survive treatment with small-molecule EGFR-targeted therapies are thus synthetically dependent on ATM, and combined treatment with an ATM kinase inhibitor eradicates these cells in vivo." (PMID 35353542, 2022). "As expected, mutations in the AR and DNA repair genes included in our panel were the most common ones, in particular, the ATM and BRCA1/BRCA2 genes, and they seemed to drive high tumor mutation load and rapid polymetastatic spread after the first oligorecurrence treated with SBRT." (PMID 35740343, 2022). "Experiments carried out on NPC cells showed that this lncRNA might be a radiosensitizing tumor suppressor reducing these types of molecular pathways through the ATM/ATR-Chk1/Chk2 signaling axis." (PMID 36294743, 2022). "Interestingly, inhibition of Ataxia Telangiectasia Mutated (ATM) results in reversion of the EMT phenotype in cisplatin-resistant NSCLC cells, inhibiting cell invasion and tumor metastasis." (PMID 35955773, 2022). "The expression of MUS81 could be upregulated in CRPC, which mediated the growth of tumor cells through ATM." (PMID 35910852, 2022). "We performed tumor surveillance for the patient with a FH (HLRCC; OMIM #150800) and ATM mutations." (PMID 35719373, 2022). "Further investigation is necessary to elaborate the effect of combined EZH2/ATM inhibition on DNA damage-derived cytosolic DNA fragments that could trigger an anti-tumor immune response." (PMID 35715861, 2022). "Like p27, ATM also play a role in promoting apoptosis and suppressing tumor development." (PMID 36339710, 2022). "When activated ATM was phosphorylated (p-ATM), it enhanced the growth of tumor cells." (PMID 35910852, 2022). "The combined treatment of PTENmut NSCLC by IR and ATM inhibition led to marked tumor regression." (PMID 35477555, 2022). "Our western blotting experiment showed that ERK signaling as well as ATM/ATR signaling was attenuated by the downregulation of hnRNP G‐T and ZDHHC11, supporting that the hnRNP G‐T‐ZDHHC11 pathway promoted tumor progression, which mediated the ATM/ATR signaling pathway." (PMID 35384384, 2022). "As a consequence, whether pharmacological ATM inhibition can radiosensitize the tumor depends on the status of a number of other, partially identified, genes." (PMID 34445646, 2021). "Moreover, there were significant correlations between ATM promoter methylation, age, tumor size, and advanced tumor stages." (PMID 33883026, 2021). "Hence, the recent studies have prevalently focused on the biological mechanism in tumor cells devoid of functional ATM, such as synthetic lethal approach using poly-ADP ribose polymerase (PARP) inhibitors." (PMID 34545188, 2021). "Moreover, ATM signaling induces tumor progression via the NF-kb-dependent pathway that promotes the release of pro-tumorigenic cytokines, as well as the epithelial–mesenchymal transition." (PMID 34068084, 2021). "Regarding the female dogs, we sequenced 79 BC-related genes, and those with high number of variants shared by tumor fragments and plasma were GATA3 and mTOR (missense), SFRP1 (frameshift insertion), BRCA2 (multi hit), FOXC2, ATM, TGFBR3, and BRIP1 (missense and multi hit mutations)." (PMID 34680380, 2021). "Therefore, ATM is crucial to maintaining the stability of the cell genome and preventing tumour occurrence." (PMID 34565365, 2021).
tumor (continued). "However, Hint1 reportedly functions as a tumor suppressor by activating ATM and the subsequent DDR20." (PMID 33953175, 2021). "In patient 13 (previously reported as patient 1 by our group in another publication), the orbital relapse showed an 11q loss spanning ATM that was absent in the primary tumor." (PMID 33567541, 2021). "However, mice treated with both 673A and an ATM or ATR inhibitor had even greater reductions in tumor volume." (PMID 33664846, 2021). "In vivo, tumor growth of CRT-resistant T24R cells was abrogated by ATM inhibition using AZD0156." (PMID 34545188, 2021). "In addition, the phosphorylation expression levels of PI3K, AKT, ATR and ATM decreased in the combination therapy compared with monotherapy or vehicle in subcutaneous tumours." (PMID 34761497, 2021). "Using targeted next-generation sequencing analysis of tumor biopsies and germline DNA samples from mCRPC patients one study found that presence of deleterious DDR mutations in BRCA2, ATM, mismatch repair (MMR), and CDK12 genes was more frequent in patients with high tumor membranous PSMA expression." (PMID 34207069, 2021). "The persistence of clonal mutations in ATM, PTK2, GLI3 and CLTCL1 in all tumour locations analysed in samples from diagnosis and at relapse in patient CB1002 could indicate the relevance of these SNVs for tumour progression." (PMID 34815394, 2021). "Mechanistic investigations showed that the ATM inhibitor KU-60019 in combination with CX-4945 induced a strong inhibition of tumor cell proliferation, reduction of cell migration and reactive oxygen species (ROS)-dependent apoptosis in HIF-2α-expressing VHL-deficient cells." (PMID 33540838, 2021). "Additionally, this illustrates the inverse, i.e., that the ATM is tumor-suppressive whereas the ATR is oncogenic." (PMID 34069817, 2021). "Therefore, ATM is essential to maintaining the stability of the cell genome and preventing the occurrence of tumours." (PMID 34565365, 2021). "Altogether, these findings reveal the non-canonical function of DGCR8 in DSB repair and suggest that radiation treatment may result in therapy-induced tumor radioresistance through ATM- and USP51-mediated activation and upregulation of DGCR8." (PMID 34188037, 2021). "Interestingly, the tumor suppressor candidates on 11q23 include; ATM, CHEK1 and H2AFX, all of which coalesce within the same DNA damage response pathways, which have been shown to be active at the G1 restriction checkpoint." (PMID 32312269, 2020). "for deleterious ERCC4 variants, the effectiveness of cisplatin is expected for disrupting mutations; PARP inhibitors are selectively toxic to tumours with RAD51C mutations, and tumours with ATM mutations had a positive response to cisplatin, and inhibitors of PARP1, ATR and DNA-PKc." (PMID 32756499, 2020). "There is insufficient data to indicate whether ATM and FANCC alterations are enriched in any taxonomical types, suggesting that combined tumor subtyping and mutational analysis could improve the ability to predict NAC response." (PMID 32635360, 2020).